NME1 (NME/NM23 nucleoside diphosphate kinase 1)
Diseases named in the same sentence as NME1 in open-access papers (continued):
Sharing a sentence is not in itself a finding about the gene and the disease.
breast carcinoma (continued). "In vivo, NME1, a known metastasis suppressor, is inhibited by LCFA-CoA, and its metastasis suppressor function is compromised in mouse models of breast cancer specifically under high-fat–diet conditions." (PMID 35259022, 2022). "Our aim was to understand how vesicular NME1 and NME2 released by breast cancer cells influence the tumour microenvironment." (PMID 36010906, 2022). "Different EV fractions such as microvesicles or medium EVs (mEVs) and small EVs (sEVs), the best examples of which are exosomes, were isolated from the supernatant of NME1 and NME2 overexpressing breast carcinoma cells." (PMID 36010906, 2022). "In addition to the transcription factors analyzed in this study, the estrogen receptor-α also possesses transactivation potential to induce the NME1 promoter in several breast cancer cell lines, which may further contribute to the transcriptional activation of Nm23-H146." (PMID 33436746, 2021). "The potential implication of NME1 and its close relative NME2 protein, during the invasive DCIS-to-IBC switch during breast cancer progression has been overlooked." (PMID 34012098, 2021). "To investigate the functional consequences of genetically modifying expression of NME1 and NME2 in MCF10DCIS.com breast carcinoma cells, we studied their cell–cell adhesion properties." (PMID 33918324, 2021). "Down-modulation of NME1 NDPK expression is known to correlate with metastatic dissemination and worse prognosis in several cancer types, including breast cancers." (PMID 34012098, 2021). "NME1 (previously termed NM23-H1, or nucleoside diphosphate kinase-A/NDPK-A) is an MSG prototype, exhibiting reduced expression and metastasis suppressor function in melanoma, breast carcinoma, and other human cancers." (PMID 32824412, 2020). "Some highly metastatic types of breast cancer show decreased intracellular levels of the tumor suppressor protein NME1, also known as nm23-H1 or nucleoside diphosphate kinase A (NDPK-A), which decreases cancer cell motility and metastasis." (PMID 32384736, 2020). "LG2 markers include 190 genes, among which are many oncogenes, (BCL2 (down, breast cancer poor prognosis marker), RAD51 (up), EGFR (up), RUNX3 (up), BCL9 (down) and VAV3 (down) and tumor suppressor gene NME1 (up)." (PMID 17683614, 2007). "Interestingly, when we tested the breast cancer cell line MCF7, we found that reduced NME1 levels unexpectedly promoted increased proliferation of these cells, suggesting that NME1 acts more in line with its established tumor suppressor role (bottom)." (PMID 39483891, 2024). "The study also showed that the increased production of cellular LCFA-CoA inhibited clathrin-mediated endocytosis, an NME1/2-dependent process, and that LCFA-CoA compromised the metastasis suppressor function of NME1 in mouse models of breast cancer under high-fat diet (HFD) conditions." (PMID 37672589, 2023). "NME1 drives the endocytosis of MT1-MMP and destructs the balance of internalization of recycling during breast cancer stays as DCIS, which could potentially result in the lysosomal destruction of MT1-MMP." (PMID 37681919, 2023). "NME1 protein level is down-regulated in metastatic breast cancer cell lines compared to nontransformed or nonmetastatic cell lines." (PMID 35259022, 2022). "We noted that the forced expression levels of WT and R58E mutant of NME1 were not higher than the levels of NME1 in nonmetastatic breast cancer cell lines." (PMID 35259022, 2022). "Given that LCFA-CoA could inhibit NME, we hypothesized that NME1 inhibition by LCFA-CoA could provide a key molecular link between fatty acid uptake/metabolism and breast cancer metastasis." (PMID 35259022, 2022). "NME1/NM23-H1 nucleoside diphosphate kinase is a well-recognized metastasis inhibitor, with NME1 downregulation influencing in situ-to-invasive shift in the process of breast cancer development." (PMID 35957812, 2022).
breast carcinoma (continued). "In this study, we analyzed the promoter region of NME1 using bioinformatic tools and reporter genes to identify novel transcription factors regulating Nm23-H1 expression in breast cancer cells." (PMID 33436746, 2021). "Whether these different regulatory circuits play a role in the biphasic NME1 expression profile and MT1-MMP up-regulation during breast cancer progression will be interesting to examine in future studies." (PMID 34012098, 2021). "NME1 can be transcriptionally regulated by a multitude of transcription factors, in particular by CTCF and EGR1, which potentially drive Nm23-H1 expression in breast cancer cells to promote a less metastatic phenotype." (PMID 33436746, 2021). "Immunoblot analysis in breast cancer cell lines with genetically-modified NME1 or NME2 levels revealed no gross alteration of total MT1-MMP levels." (PMID 34012098, 2021). "NME expression was investigated by IHC analysis on whole sections and on a tissue microarray (TMA) of synchronous DCIS and IBC foci from 156 breast cancer patient samples using specific NME1 pAb and NME2 mAb with no cross-reactivity." (PMID 34012098, 2021). "Recent findings indicate that NME1′s ability to suppress motility depends on its protein kinase function, as neither mutant is able to inhibit migration of transfected MDA-MB-231 and MDA-MB-435 breast cancer cells." (PMID 32823988, 2020). "The human breast carcinoma cell line MDA-MB-231 was used as model in this study because these cells are highly metastatic and show relatively low basal expression levels of endogenous NDPK-A/NME1." (PMID 32384736, 2020). "Thus, its metastasis-suppressing function in certain breast cancer types, especially those with a decreased level in NDPK-A/NME1 expression, is well established and at least partially understood." (PMID 32384736, 2020). "Interestingly, all those changes have a clearly anti-metastatic trend - re-expression of GLCE in breast cancer cells MCF7 up-regulates the expression of suppressor genes SYK and NME1 and down-regulates the expression of metastasis marker S1004A and TGFβ." (PMID 20723247, 2010). "For genes related to breast cancer estrogen signaling, GSEA analysis showed a progressive down-regulation of keratin 18 and NME1 from luminal A to basal tumors, which also correlated with ER(+)ve MDA-MB-435 cells; low expression of these genes correlates to poor prognosis and metastasis." (PMID 17883861, 2007). "We found that NME1, which is a metastasis suppressor, can be inhibited by LCFA-CoA, highlighting a molecular mechanism that may impact how fatty acid metabolism affects breast cancer metastasis." (PMID 35259022, 2022). "To test this prediction, we searched the Molecular Taxonomy of Breast Cancer International Consortium (METABRIC) database—which contains the clinical and biological data for 1904 human breast tumors—looking for relationships between mRNA levels of NME1 and epithelial and mesenchymal markers." (PMID 33918324, 2021). "However, only the lack of expression of nme1 has been related to distant metastasis appearance in human breast cancer." (PMID 8605098, 1996). "The role of NME1 in EMT has not been extensively studied, but one study demonstrated that depletion of NME1 promotes EMT in breast cancer (BCa), showing that NME1 is an inhibitor of EMT." (PMID 39063217, 2024). "Overexpression of NME1, but not its highly related isoform NME2, has been reported to suppress cell migration in multiple highly invasive breast cancer cell lines." (PMID 35259022, 2022). "NME1 is a metastasis-suppressor gene (MSG), capable of suppressing metastatic activity in cell lines of melanoma, breast carcinoma and other cancer origins without affecting their growth in culture or as primary tumours." (PMID 33024267, 2021). "Collectively, these data indicate that metastasis-suppressor NME1, but not NME2, controls the endocytic clearance and surface exposure of MT1-MMP in various breast cancer cell lines." (PMID 34012098, 2021).
breast carcinoma (continued). "Nucleoside diphosphate kinase, NME1/NM23-H1, has been identified as a metastasis suppressor; however, its contribution to local invasion in breast cancer is not known." (PMID 34012098, 2021).
melanoma (62 papers, 1993 to 2025). A malignant, usually aggressive tumor composed of atypical, neoplastic melanocytes. "The expression of ITGB3 RNA was linked with prolonged survival of melanoma patients, supporting its potential role as an effector in the metastasis suppressor function of NME1." (PMID 39796775, 2025). "Reduced NME1 expression in melanoma cell lines, mouse models of melanoma, and melanoma specimens in human patients is associated with increased metastatic activity." (PMID 32824412, 2020). "In this regard, we showed that point mutations disabling the 3′-5′ exonuclease activity of NME1 are associated with loss of metastasis suppressor function in melanoma cells." (PMID 32824412, 2020). "A huge interest for these enzymes was raised in the early 1990s when it was suggested that the gene encoding NME1 was responsible for metastasis suppression in a murine melanoma model system." (PMID 32235358, 2020). "Both enzymatic activities have been suggested to contribute to the metastasis suppressor function of NME1 in melanoma cells, although the underlying molecular mechanisms have yet to be identified." (PMID 28788083, 2017). "To this end, we crossed the HGF/SF and NME1/2+/− mouse strains in a C57BL/6 genetic background to measure the impact of NME1/NME2 deficiency on the metastatic potential of UV-induced melanoma." (PMID 28788083, 2017). "In addition, numerous studies analyzing human patients with melanoma or epithelial tumors of the breast, liver, colon or ovary, found that loss of NME1 expression correlated with a greater risk of metastasis and a poorer clinical prognosis." (PMID 37353690, 2023). "As these measurements of NME1 expression were conducted in whole tumor specimens, they did not address the possible existence of rare subpopulations of NME1-deficient cells which could well possess enhanced metastatic properties and represent a stronger index of melanoma progression." (PMID 32029850, 2020). "Another protein, NME1, is involved in oxidative stress response and its increased expression correlates with tumor aggressiveness in specific cancer types (melanoma, liver and breast)." (PMID 40342827, 2025). "In melanoma, NME1 interacts with the p110 subunit of PI3K, inhibiting p110 function and phosphorylation of AKT." (PMID 39063217, 2024). "On the one hand, NME1 expression was originally identified as a suppressor of metastasis in melanoma and epithelial cancers." (PMID 39063217, 2024). "NME1 decreases the invasion of cancer cells in BCa, melanoma, hepatoma, HCC, colon carcinoma (CRC), and neuroblastoma." (PMID 39063217, 2024). "By contrast, silencing NME1 in non-invasive tumor cell lines that express high NME1 levels, results in a migratory and invasive phenotype in melanoma, glioblastoma, and carcinoma cells." (PMID 37353690, 2023). "NME1 expression shows an inverse correlation with metastatic potential in melanoma, hepatocellular, breast and colon carcinoma, meaning that low NME1 level is connected to higher probability of metastasis formation in numerous tumour types." (PMID 36010906, 2022). "High expression of NME1 promoted cell proliferation, growth of melanoma spheres and stem-cell-like features, whereas NME1low cells were more aggressive and metastatic while exhibiting neural crest-like features." (PMID 35740696, 2022). "NME1 has been identified as the first metastasis suppressor, showing reduced expression in high melanoma metastatic cells and as a suppressor of breast, liver, and colon carcinoma metastasis through mechanisms that are not yet well-understood." (PMID 36111347, 2022). "In recent studies, NME1 demonstrated interesting characteristics depending on its expression level in melanoma cells." (PMID 35740696, 2022). "Together, these findings provide the first demonstration of metastasis-suppressor activity for Nme1 in an in vivo context of spontaneous melanoma." (PMID 33024267, 2021).
melanoma (continued). "The study ascribes MSG activity to Nme2 for the first time in an in vivo model of spontaneous cancer, as well as a novel metastasis-suppressor function to Nme1 in the specific context of UVR-induced melanoma." (PMID 33024267, 2021). "This approach demonstrated robust MSG activity of Nme2 for the first time in any model of spontaneous cancer, while revealing strong suppressor activity of Nme1 in UVR-induced melanoma." (PMID 33024267, 2021). "This study demonstrates that the ablation of either Nme1 or Nme2 confers robust increases in metastatic activity in the HGF-based mouse model of UV-induced melanoma." (PMID 33024267, 2021). "Having shown that NME1 is also recruited to DSBs conferred by γ-IR treatment in the melanoma cell line WM793, we elected to analyze the impacts of NME1 on DSBR in the specific setting of melanoma-derived cell lines." (PMID 32824412, 2020). "Conversely, these studies indicate that low NME1 expression in melanoma cells results in reprogramming of DSBR activities to increase genomic stability." (PMID 32824412, 2020). "Our laboratory has previously demonstrated in melanoma cell lines that NME1 expression enhances repair of ultraviolet light-induced DNA damage." (PMID 32824412, 2020). "In contrast, our results obtained with melanoma cells show that NME1 depletion promotes both NHEJ and HR activity, but is required for the more highly error-prone A-NHEJ." (PMID 32824412, 2020). "We first reported that NME1 is recruited to DSBs in melanoma cell lines, and this has recently been confirmed." (PMID 32824412, 2020). "Identical results were obtained across all DSBR pathways in clones derived from both parental WM35 and WM164 cell lines, suggesting the impact of NME1 is exerted across early and late stages of melanoma progression." (PMID 32824412, 2020). "NME1 suppresses motile and invasive phenotypes of melanoma cells by inducing the transcription of integrin beta-3 (ITGβ3) gene through direct physical interaction with the promoter." (PMID 32977620, 2020). "We also show that in the specific setting of human melanoma cells, NME1 expression exerts a suppressive influence on the higher-fidelity HR and NHEJ pathways while enhancing the lower fidelity A-NHEJ pathway." (PMID 32824412, 2020). "We have identified a rare subpopulation of cells with markedly reduced expression of NME1 (NME1LOW) in human melanoma cell lines." (PMID 32029850, 2020). "NME1 is a metastasis suppressor of murine melanoma cells and a broad spectrum of human tumours including breast, thyroid and gastric cancers." (PMID 30952991, 2019). "In this review, we summarize how the HGF/SF transgenic mouse has been used to reveal metastasis-regulating activity of four different genes (CDK4R24C, survivin and NME1/NME2) in the context of UV-induced melanoma." (PMID 28788083, 2017). "While studies conducted in cancer cell lines strongly suggested NME1 possesses metastasis suppressor activity, the activity had yet to be validated in a model of spontaneous melanoma in vivo." (PMID 28788083, 2017). "In particular, the HGF/SF × NME1/2+/− hybrid exhibits a tropism of metastases (lymph node > lung > liver > bone, brain, etc.)that is nearly identical to that observed in human melanoma." (PMID 28788083, 2017). "The metastasis-suppressor nme gene (also called nm23), first identified in murine melanoma cells, exists as two forms in human: nme1 and nme2." (PMID 8605098, 1996). "However, a recent paper showed that NME1 enhances the growth of melanoma spheres in culture, tumor growth, and metastasis to the lung in vivo." (PMID 39063217, 2024). "In melanoma, NME1 promotes focal adhesion through the integrin β3 (ITGβ3) protein." (PMID 39063217, 2024).
melanoma (continued). "First, up-regulation of NME1 in several metastatic tumor cell lines from multiple histological types, including melanoma, breast, colon, lung, liver, ovary, prostate, and oral carcinoma cell lines, reduced their metastatic potential both in experimental and spontaneous mouse models of metastasis." (PMID 37353690, 2023). "Transcription of ITGB3 gene induces the expression of NME1, a metastatic suppressor, in melanoma." (PMID 34660316, 2021). "Increased metastatic activity in HPN1 and HPN2 mice was associated with Nme1 or Nme2 inactivation and was not secondary to growth characteristics of melanomas or tumour burden (e.g., size or number)." (PMID 33024267, 2021). "Interestingly, NME1/NM23-H1 has been identified as the first metastasis suppressor, showing reduced expression in highly melanoma metastatic cells and as a suppressor of breast, liver, and colon carcinoma metastasis." (PMID 34012098, 2021). "In melanoma, NME1 has been shown to inhibit metastasis by activating ALDOC transcription." (PMID 33737938, 2021). "An inhibitory activity of NME1 in cancer metastasis was further suggested by an inverse correlation between NME1 expression and poor clinical outcome observed across a spectrum of human cancers, including melanoma." (PMID 28788083, 2017). "In light of the DNA repair and transcription functions of NME1, we are also using NextGen sequencing to compare mutational and transcriptional profiles in UV-induced melanomas (both primary and metastatic tumors) between the HGF/SF and HGF/SF × NME1/2+/− hybrid strains." (PMID 28788083, 2017). "The DNA repair-promoting activity of NME1 and/or NME2 suggests loss of their expression could promote acquisition of mutations that accelerate melanoma progression." (PMID 28788083, 2017). "Interestingly, NME1 was first demonstrated as a suppressor of metastasis in melanoma." (PMID 39063217, 2024). "These considerations suggested the hypothesis that reduced NME1 expression in melanoma cells not only confers increased metastatic activity, but also enhanced genomic stability via downregulation of the low fidelity A-NHEJ pathway and upregulation of the higher fidelity HR and C-NHEJ pathways." (PMID 32824412, 2020). "Through analysis of the protein expression pattern for the metastasis suppressor protein, NME1, we have discovered a previously unidentified subpopulation present within melanoma cell lines that is highly metastatic and may well represent a barrier to successful therapy in melanoma patients." (PMID 32029850, 2020). "A decreased level of NME1 and NME2 metastasis suppressor proteins were found in WM793B-resistant primary melanoma, which is possibly the result of vemurafenib-acquired resistance and is one of the causes of increased PI3K/AKT signaling." (PMID 36077308, 2022). "Herein, we selectively ablated the tandemly arranged Nme1 and Nme2 genes to assess their individual impacts on metastatic activity in a mouse model (HGF:p16−/−) of ultraviolet radiation (UVR)-induced melanoma." (PMID 33024267, 2021). "Herein, we investigate the role of NME1 in repair of double-stranded breaks (DSBs) and choice of double-strand break repair (DSBR) pathways in melanoma cells." (PMID 32824412, 2020). "Together, these findings indicate that NME1 suppresses the higher-fidelity HR and NHEJ pathways of double-strand break repair while enhancing low-fidelity A-NHEJ in cultured human melanoma cell lines." (PMID 32824412, 2020). "The effects of NME1 depletion on these three DSBR pathways were exerted in cell lines representing both early stage (WM35) and metastatic (WM164) melanoma, strongly suggesting the genome-stabilizing effect of NME1 appears early in melanoma progression." (PMID 32824412, 2020). "A small subpopulation of cells was identified that expressed low amounts of NME1 protein (NME1LOW) in cell lines derived from both metastatic (WM9) and vertical growth phase (WM278) melanomas." (PMID 32029850, 2020).